GPX4 (glutathione peroxidase 4)
Diseases named in the same sentence as GPX4 in open-access papers (continued):
Sharing a sentence is not in itself a finding about the gene and the disease.
Sepsis (continued). "The observed reductions in nonheme iron content and alterations in ferroptosis-related proteins, particularly GPX4 and ACSL4, underscore the significant role of iron metabolism and ROS management in sepsis treatment strategies." (PMID 39857660, 2024). "Previous research has found that GPX4 expression and lipid peroxidation were involved in GSDMD-mediated pyroptosis in sepsis." (PMID 38891111, 2024). "Western blot analysis of ferroptosis-related proteins revealed that sepsis altered the expression of 4-HNE, FTH1, GPX4, ACSL4, PTGS2, and SLC7A11, which was reversed by ghrelin and Fer-1, indicating their role in inhibiting ferroptosis." (PMID 39857660, 2024). "Overall, our findings demonstrated that PRDM16 suppresses ferroptosis via the NRF2/GPX4 axis or directly through GPX4, as confirmed by PT-PRDM16-KO, PT-PRDM16-KI, and ADV-PRDM16 plasmid experiments in sepsis mice induced by CLP." (PMID 39549609, 2024). "Exosomes derived from ECs that overexpressed miR-125b-5 were found to prevent acute lung injury (ALI) induced by sepsis by inhibiting TOP2A and alleviate inflammation-induced iron death by upregulating GPX4." (PMID 38343439, 2023). "In a mouse model of sepsis-induced myocardial injury, matrine protects the damaged myocardium by activating the PI3K/AKT pathway to upregulate GPX4 expression and downregulate ACSL4 expression to inhibit ferroptosis." (PMID 37954843, 2023). "In sepsis-induced ARDS, treatment of lipopolysaccharide (LPS) can significantly suppress the expression level of GPX4 and SLC7A11, while the level of MDA, 4-HNE, and total iron is strikingly increased." (PMID 36898986, 2023). "iFSP1+RSL3 inhibited both GPX4 and FSP1, further reversing the effect of APAP on the reduction in iron, 4‐HNE, ROS, and MDA levels in the cerebral hippocampus of mice with sepsis." (PMID 37443407, 2023). "Irisin can affect GPX4 expression and attenuate ferroptosis in LPS-treated hepatocytes and CLP sepsis mouse models." (PMID 35990689, 2022). "Dexmedetomidine, a α2-adrenergic receptor (α2-AR) agonist, reduces myocardial iron concentration by reducing sepsis induced Hmox-1 overexpression, decreases inflammatory cytokines IL6 and MCP-1 expression, and increased GPX4 activity to reduce cardiac injury." (PMID 35153792, 2022). "In a sepsis model, DEX can reduce ferroptosis and protect important organ damage by enhancing glutathione peroxidase 4 (GPX4) expression." (PMID 36313359, 2022). "GPX4 and TFRC played an important role in ferroptosis, so it was necessary to analyze the difference between sepsis and control." (PMID 35844488, 2022). "GPX4 knockout activated the lipid peroxidation-dependent caspase-11, which triggered the GSDMD cleavage to induce pyroptosis during polymicrobial sepsis." (PMID 34820376, 2021). "One study has shown that in lipopolysaccharide (LPS)-induced sepsis models, the levels of iron and ROS in alveolar epithelial cells were increased significantly, while GSH levels were decreased, and the expression of GPX4 and SLC7A11 was significantly downregulated." (PMID 41250137, 2025). "Combined targeting of GPX4 (e.g., via GSH replenishment) and FSP1 (e.g., using CoQ10 analogs like idebenone) may offer synergistic benefits in mitigating sepsis-induced ferroptosis." (PMID 40893878, 2025). "Consequently, administration of exogenous HNE or increasing endogenous HNE levels by impeding glutathione peroxidase 4 (GPX4), which attenuates HNE formation, inhibited inflammasome activation during acute lung injury and sepsis in mice." (PMID 39327931, 2025). "Concurrently, sepsis depletes GSH by downregulating the xCT transporter, impairing GPX4 activity." (PMID 41383584, 2025). "The findings indicate that BAT-derived Nrg4 suppresses ferroptosis and attenuates sepsis-induced liver injury by promoting the expression of SLC7A11, GSH, and GPX4, suggesting potential therapeutic application of BAT activation and its secreted Nrg4 in treating septic liver injury." (PMID 39956880, 2025).
Sepsis (continued). "Mir22hg silencing lightened ferroptosis and ferritinophagy in LPS-induced MLE-12 cells and sepsis mouse models, as presented by the downregulated MDA, ROS, Fe2+, NCOA4, and SLC3A2 levels, upregulated GPX4, GSH, and FTH1 levels, along with a decrease in autophagy." (PMID 38842666, 2024). "Notably, this study also demonstrated that these decreases in the expression of Gpx4 and GSH in the liver and lungs in mice with CLP-surgery-induced sepsis were reversed by suppressing SP-NK1R signalling." (PMID 38539834, 2024). "Furthermore, the increase in ROS causes an increase in iron content and alterations in the proteins GPX4, ACSL4, and SLC7A11, recognizing the role of ferroptosis in sepsis-related brain degeneration." (PMID 39768830, 2024). "Moreover, the peritoneal administration of HNE or the GPX4 inhibitor RSL3, mitigated LPS-induced acute lung injury and sepsis by decreasing IL-1β and IL-18 secretion in vivo." (PMID 36944609, 2023). "In myeloid conditional GPX4-knockout mice, the lipid peroxidation rate was increased, which promoted GSDMD-dependent pyroptosis in macrophages via driving caspase-11 activation, leading to increased sepsis-induced lethality." (PMID 36944609, 2023). "The levels of ROS, Fe ion, GSH, GPX4, and MDA at model + miR-9-5p angomir rats came close to that of control rats and significantly differed from that in model rats, which indicated that increased miR-9-5p in rats alleviated sepsis-induced ferroptosis." (PMID 35038133, 2022). "The results demonstrated that sepsis-induced prominent inflammatory responses, intense oxidative stress, ROS release, intracellular iron accumulation, lipid peroxidation, and upregulation of HO-1, accompanied by a marked downregulation of XCT and GPX4 expression." (PMID 40595455, 2025). "The administration of the antioxidant vitamin E, rather than liproxstatin-1, prevents polymicrobial sepsis in Gpx4 conditional knockout mice in myeloid cells, suggesting that ferroptosis is not required for Gpx4 depletion-induced cell death in myeloid cells responding to bacterial infections." (PMID 38844964, 2024). "In a mouse model of sepsis, NETs induced iron death in alveolar epithelial cells through activation of METTL3-m6A modification, a pathway that contributes to lung injury and systemic inflammation by promoting iron death via the NETs/p300/H3K27ac/METTL3-m6A/IGF2BP2-m6A/HIF-1α/GPX4/ROS pathway." (PMID 39108751, 2024). "IHC results depicted that GPX4, a key molecule of ferroptosis, was considerably lower in the CLP group in comparison with the sham and sham + DMSO groups, and was further decreased by erastin treatment, while Fer-1 treatment ameliorated the sepsis-induced GPX4 reduction." (PMID 39097582, 2024). "This is intimately connected to the primary ferroptosis pathways GPX4 and FSP1.GPX4 is the main role In GSH‐Px, FSP1 indirectly suppresses ferroptosis via vitamin E. In the present study, we suggest that APAP inhibits ferroptosis in mice with sepsis via the GPX4 and FSP1 pathways." (PMID 37443407, 2023). "Baseline serum levels of ACSL4, GPX4, PTGS2, CL-11, IL-6, IL-8, PCT, and hs-CRP significantly differed among sepsis, non-septic, and healthy individuals (all p-value < 0.01)." (PMID 40264754, 2025). "GPX4 reduces LPO to non-toxic alcohols by using GSH, but this system is compromised in sepsis-induced ARDS." (PMID 41383584, 2025). "For differentiating sepsis from non-sepsis in ICU patients, IL-8, ACSL4, GPX4, CRP, PCT, NEU%, IL-6, and PTGS2(p-value =0.007) exhibited significant diagnostic value (all p-value <0.00001)." (PMID 40264754, 2025).
acute kidney injury (114 papers, 2019 to 2025). Sudden and sustained deterioration of the kidney function characterized by decreased glomerular filtration rate, increased serum creatinine or oliguria. "It is highly possible that targeting Smad3 with Smad3 inhibitors such as SIS3 inhibits renal fibrosis as well as acute kidney injury via a mechanism associated with GPX4-dependent ferroptosis as seen in this study and other previous reports." (PMID 41079940, 2025). "The conditional knockout of GPX4 is linked with cancer, neurodegenerative diseases, acute kidney injury or liver injury, preventable or mitigated by inhibiting ferroptosis." (PMID 40141980, 2025). "Recent studies of acute kidney injury implicated LGMN in the degradation of glutathione peroxidase 4 (GPX4), a key protective factor against ferroptosis, through molecular chaperone-mediated lysosomal autophagy." (PMID 39104790, 2024). "Preclinical investigations further confirmed the critical role of GPx4, as inducible Gpx4(-/-) mice generated in subsequent studies succumbed to acute kidney failure within two weeks of Gpx4 loss." (PMID 39279996, 2024). "They demonstrated a critical role for the GSH/Gpx4 axis in the prevention of lipid-oxidation-stimulated acute renal failure and associated death using inducible Gpx4(−/−) mice." (PMID 38203174, 2023). "Inducible Gpx4 knockout mice directly aggravate lipid-oxidation-induced acute kidney injury and associated death." (PMID 36923942, 2023). "At the genetic level, GPX4 knockout mice develop renal failure due to the loss of GPX4’s inhibitory effect on ferroptosis." (PMID 35990689, 2022). "Using inducible GPX4(−/−) mice, a major study elucidated the essential role for the glutathione/GPX4 axis in preventing lipid-oxidation-induced acute renal failure and associated death." (PMID 36613888, 2022). "In GPx4 knockout mice, GPx4 deficiency leads to spontaneous acute renal failure and an increased rate of early mortality, whereas ferroptosis of renal tubular epithelial cells is the main cause of renal failure in GPx4 knockout mice." (PMID 35873574, 2022). "Neuron-specific deletion or inducible depletion of GPX4 causes neurodegeneration and acute renal failure, respectively, with an increase in lipid peroxidation, suggesting that GPX4 is a critical suppressor of lipid peroxidation and related pathologies." (PMID 33801564, 2021). "Notably, acute kidney injury, a hallmark feature of full-body GPX4 deletion in mice, has been observed as adverse effect in ibrutinib-treated patients." (PMID 41173858, 2025). "Although ACE induces ferroptosis in tumor cells by targeting PCBP1/2 and GPX4, previous studies have shown that ferroptosis may cause acute liver injury and acute kidney injury." (PMID 40619432, 2025). "The deficiency of GPX4 is recognized as a biomarker for ferroptosis, and the inhibition of GPX4 could induce acute renal failure induced by lipid oxidation, leading to associated ferroptosis." (PMID 39735782, 2024). "Furthermore, GPx4 knockout (KO) is known to cause acute renal failure and death, suggesting that GPx4 plays an essential role as an antioxidant in mitochondria." (PMID 38275757, 2024). "However, the direct inhibition of GPX4 requires caution, as GPX4 deficiency can cause severe side effects, such as acute kidney failure and embryonic lethality." (PMID 39568772, 2024). "It has been discovered that legumin can mediate the development of acute kidney damage by controlling the degradation of GPX4, legumin and GPX4 can interact to promote autophagy, legumin deficiency can ameliorate acute kidney injury in mice, and legumin is a key target of acute kidney injury." (PMID 38590315, 2024). "The present results showed that cisplatin induced mitochondrial injury, ROS release, intracellular iron accumulation, lipid peroxidation, HO1 signaling upregulation, and GPX4 loss, which resulted in renal tubular epithelial cell ferroptosis and acute kidney injury." (PMID 36923942, 2023).
acute kidney injury (continued). "A deficiency in Gpx4 activity contributes to ferroptosis in cancer cells and renal failure." (PMID 32362442, 2020). "Notably, a deficiency in GPX4 has been demonstrated to significantly enhance iron‐induced cell death in the epithelial cells of the renal tubules, ultimately leading to the development of acute renal failure." (PMID 38812118, 2024). "In addition, the inactivated ferritin regulator GPX4 can cause acute renal failure in mice." (PMID 34422728, 2021). "For instance, both protopanaxadiol and baicalein have been proven to improve cisplatin-induced acute kidney injury, but their effects are mainly limited to different ferroptosis pathways—targeting GPX4 and ALOX12, respectively." (PMID 41303615, 2025). "In acute kidney injury, histone deacetylase 3(HDAC3) mutations can cause GPX4 inhibition, promote ferroptosis of renal epithelial cells, and aggravate AKI development." (PMID 40959280, 2025). "Despite the potential side effects of GPX4 inhibitors, for example, GPX4 inactivation triggers acute renal failure and hepatic ischemia/reperfusion injury." (PMID 40619432, 2025). "Recent studies have shown that SeNPs inhibit ferroptosis by enhancing glutathione peroxidase 4 (GPX4) expression, alleviating brain ischemia-reperfusion injury, acute kidney injury, and acute lung injury." (PMID 41019494, 2025). "Mice with a knockout of the GPX4 gene succumb to renal failure, and inhibitors of GPX4 have shown promise in enhancing the efficacy of treatments against drug-resistant, persistent cancer cells." (PMID 41242017, 2025). "In sepsis-associated acute kidney injury, suppression of NRF2 expression leads to a reduction in GPX4 levels, consequently increasing Fe2+ and reactive oxygen species (ROS) generation, which exacerbates ferroptosis and accelerates AKI progression." (PMID 41356483, 2025). "Conducted research on this matter indicate that inactivation of the ferroptosis regulator glutathione peroxidase 4 (GPX4) can directly induce acute renal failure by triggering iron toxicity in mouse renal tubular cells." (PMID 38753279, 2024). "Rosiglitazone can reduce the level of arachidonic acid, similar to the level of ACSL4 knockout cells, and also improve the survival rate of Gpx4 knockout mice to avoid renal failure death." (PMID 39872050, 2024). "Transgenic studies in mice have shown that proximal renal tubule cells are particularly sensitive to ferroptosis outside of the brain, as evidenced by the spontaneous development of acute renal failure in tamoxifen‐induced Gpx4 knockout mice." (PMID 39568772, 2024). "In prior studies, the genetic ablation of the ferroptosis regulator GPX4 resulted in acute kidney injury in murine models, ultimately culminating in mortality." (PMID 39839617, 2024). "Quercetin (QCT) significantly inhibits SLC7A11 and GPX4 expression and ameliorates macrophage chemotaxis in acute kidney injury." (PMID 39687171, 2024). "Here, the authors demonstrate that the OTUD5 interaction with GPX4 is key in resisting ischemia/reperfusion-induced ferroptosis in renal cells, offering a new strategy for treating acute kidney injury." (PMID 38110369, 2023). "Studies have demonstrated that ferroptosis inhibitors alleviate renal tubular cell death and acute kidney failure in models of renal tubular cell IRI in mice, GPX4 knockout mice, and folate-induced acute kidney injury models." (PMID 38562992, 2023). "A recent study further proposed that GPX4 plays an essential role in preventing lipid peroxidation-induced ferroptosis and acute renal failure." (PMID 37121999, 2023). "Previous studies have reported that VDR can regulate ferroptosis via GPX4 in cognitive dysfunction and acute kidney injury." (PMID 36846715, 2023). "Number 5 on the list was “Inactivation of the Ferroptosis Regulator Gpx4 Triggers Acute Renal Failure in Mice” with a total of 1634 citations." (PMID 37600367, 2023).
acute kidney injury (continued). "Inducible deletion of GPX4 led to mouse death within a few weeks due to acute renal failure, which was markedly delayed in mice treated with liproxstatin-1, a ferroptosis inhibitor, and lipophilic RTA20." (PMID 37612411, 2023). "Accordingly, stable expression of GPX4 is necessary for functional maintenance; GPX4 knockout mice suffer from ferroptosis and acute kidney injury, resulting in significantly shorter survival times." (PMID 36275899, 2022). "Legumain has been shown to facilitate tubular ferroptosis via the promotion of chaperone-mediated GPX4 autophagy in acute kidney injury, while the selenium-GPX4 axis reduces the ferroptosis of follicular helper T cells." (PMID 35805124, 2022). "This conclusion supports a prior study that found the GSH/GPX4 axis to be responsible for lipid oxidation-induced acute kidney injury and cell death." (PMID 35281462, 2022). "One study found that GPX4 dysfunction reduced the sensitivity of mice to acute tubular necrosis (ATN) during acute kidney injury (AKI), while Nec-1f." (PMID 36335193, 2022). "Inducible GPX4 knockout in the kidney arises massive ferroptosis of renal tubular epithelia, which results in death due to acute renal failure." (PMID 34961563, 2021). "This study used inducible Gpx4(−/−) mice to elucidate an essential role for the GSH/Gpx4 axis in preventing lipid-oxidation-induced acute renal failure." (PMID 34150654, 2021). "TRSL3 (a GPx4 inhibitor) reduced the expression of GPx4 and abolished the protective effects of irisin in I/R-induced acute kidney injury, suggesting that GPx4 is a vital component in irisin’s protective effect after renal I/R." (PMID 33317180, 2020). "As a key regulator of ferroptosis, GPX4 inhibition was previously found to trigger renal failure and exacerbate cognitive deficits via inducing ferroptotic cell death in mice." (PMID 31379480, 2019). "In a recent study using inducible GPX4-deficient mice, the mice died of massive renal tubular cell death and acute renal failure within 2 weeks after GPX4 deletion." (PMID 31781351, 2019). "Gpx4 inactivation in mice also resulted in acute renal failure, which was impeded and attenuated with liproxstatin-1." (PMID 31597407, 2019). "Furthermore, acute renal failure and early death via ferroptosis was observed in inducible Gpx4 knockout mice." (PMID 39369284, 2025). "TRIM21 ubiquitination degrades GPX4 to promote ferroptosis in acute kidney injury." (PMID 38542289, 2024). "Moreover, some research has confirmed that GPX4 is important for the development of mice, and inactivation of GPX4 can induce acute renal failure or even death in mice 203,204." (PMID 37564206, 2023). "Interestingly, TZDs showed effects on suppressing ferroptosis by selectively inhibiting ACSL415,273 in breast cancer cell lines and reduce mortality due to acute renal failure in kidney-specific Gpx4 knockout mice." (PMID 37735472, 2023). "Gpx4 is highly expressed in the proximal tubules of kidney and inducible disruption of Gpx4 leads to ferroptotic cell death of proximal tubular epithelia and acute kidney failure in mice." (PMID 36435804, 2022). "The inactivation of GPX4, the key ferroptosis regulator, can trigger ferroptosis in kidney tubular cells and induce acute renal failure, while the ferroptosis inhibitor, ferrostatin-1 (Fer-1), can prevent morphological changes in synchronized tubular cell death." (PMID 35979396, 2022). "GPX4 knockdown in mice may contribute to the ferroptosis in kidney tubular cells, inducing acute renal failure, which was efficiently suppressed by Fer-1 and DFO." (PMID 35847582, 2022). "In addition, Gpx4 knockdown in mice induced kidney iron-mediated death and acute renal failure, confirming that GPX4 is a key regulator of ferroptosis." (PMID 34659638, 2021). "Moreover, genetic ablation of GPX4 leads to early embryonic lethality, while inducible deletion of GPX4 results in acute renal failure and early death in mice." (PMID 33801920, 2021).